TNKS2 (tankyrase 2)
Diseases named in the same sentence as TNKS2 in open-access papers:
TNKS2 is named in the same sentence as 46 diseases in open-access papers, as found by Europe PMC text mining. Sharing a sentence is not in itself a finding about the gene and the disease. The quoted sentences say what the papers report.
colorectal cancer (6 papers, 2012 to 2021). A primary or metastatic malignant neoplasm that affects the colon or rectum. "miR-490-3p can suppress cell viability and resistance to chemotherapy in colorectal cancer cells through targeting TNKS2." (PMID 33849554, 2021). "For both genes, endometrial is the one that presented the highest rate of TNKS and TNKS2 mutations, followed by colorectal cancer, bladder and esophagogastric (for TNKS) and melanoma, colorectal and prostate (for TNKS2)." (PMID 33910596, 2021). "miR-490-3p could affect colorectal cancer by targeting TNKS2." (PMID 33849554, 2021). "Inhibition of the tankyrase enzymes (TNKS1 and TNKS2) has recently been shown to induce highly dynamic assemblies of β-catenin destruction complex components known as degradasomes, which promote degradation of β-catenin and reduced Wnt signaling activity in colorectal cancer cells." (PMID 28107521, 2017). "In control RKO colorectal cancer cells a similar, though more potent inhibition of the TOPFLASH reporter was observed upon abrogation of tankyrase 1 or tankyrase 2 expression." (PMID 23144924, 2012).
cervical carcinoma (5 papers, 2012 to 2023). A carcinoma arising from either the exocervical squamous epithelium or the endocervical glandular epithelium. "miR-20a promotes migration and invasion by regulating tankyrase, TRF1-interacting ankyrin-related ADP-ribose polymerase 2 (TNKS2) expression in human cervical carcinoma cells." (PMID 23799609, 2013). "Oncogenic TNKS2 is directly regulated by miR-20a, and the suppression of TNKS2 inhibits the colony formation, migration and invasion of cervical carcinoma cells." (PMID 23799609, 2013). "In human cervical cancer cells, miR-20a was reported to promote cancer cell migration and invasion by targeting Tankyrase 2 (TNKS2)." (PMID 23924943, 2013). "In addition, oncogenic TNKS2 can promote the migration and invasion of cervical cancer cells by directly upregulating miR-20a." (PMID 36213124, 2022). "miR-20a could promote migration and invasion of cervical cancer cells through the direct upregulation of TNKS2, which induced colony formation, migration and invasion of cervical cancer cells." (PMID 22922800, 2012).
lung carcinoma (4 papers, 2013 to 2021). "High levels of TNKS1 and/or TNKS2 expression have been observed mainly in colon and lung cancer, but also in brain cancer, breast cancer, ovarian cancer and liver cancer." (PMID 33910596, 2021). "We found that both TNKS1 and TNKS2 were overexpressed in human lung carcinoma, while LKB1 and p-AMPK levels were downregulated." (PMID 31554794, 2019). "Pharmacological or genetic inhibition of TNKS1 and TNKS2 antagonizes canonical Wnt signaling and reduces lung cancer proliferation in vitro and in vivo." (PMID 23621985, 2013). "Individual or combined knockdown of TNKS1 and TNKS2 with siRNAs or shRNAs reduced lung cancer cell growth, stabilized axin, and repressed tumor formation in murine xenograft and syngeneic lung cancer models." (PMID 23621985, 2013). "In addition, TNKS1 and TNKS2 levels are elevated in lung cancer, as well as β-catenin levels." (PMID 33910596, 2021). "Single knockdown of either TNKS1 or TNKS2 or dual TNKS knockdowns were growth inhibitory in the ED1, A549, and Hop62 lung cancer cell lines (respectively)." (PMID 23621985, 2013). "Microarray analyses comparing Wnt pathway members in malignant versus normal tissues of a murine transgenic cyclin E lung cancer model revealed deregulation of Wnt pathway components, including TNKS1 and TNKS2." (PMID 23621985, 2013).
breast carcinoma (3 papers, 2016 to 2024). "Notably, Salhab and colleagues, in their study, demonstrated a decreased expression of the TNKS2 gene as breast cancer progression advanced." (PMID 38339395, 2024).
glioblastoma (2 papers, 2016 to 2025). The most malignant astrocytic tumor (WHO grade IV). "miR-490* constrains proliferative capacity in glioblastoma by repressing telomere-maintenance genes Telomeric Repeat-binding Factor 2 (TERF2), Tankyrase 2 (TNKS2) and Serine/Threonine-protein kinase, (SMG1), inducing telomere dysfunction and DNA-damage signalling." (PMID 41468376, 2025).
ovarian carcinoma (2 papers, 2021 to 2022). A malignant neoplasm originating from the surface ovarian epithelium. "It was reported that TNKS2 promotes Wnt/β-catenin signaling in ovarian cancer, increasing tumor cell glycolysis and proliferation." (PMID 36185280, 2022). "Furthermore, we systematically revealed that icariin attenuates the tumor progression by suppressing TNKS2/Wnt/β-catenin signaling via upregulating the level of miR-1-3p in ovarian cancer with transcriptome analysis." (PMID 36185280, 2022).
ovarian tumor (2 papers, 2014 to 2022). "In ovarian tumor tissues, TNKS2 has been discovered to be significantly overexpressed, and PARP, including TNKS1 and TNKS2, are important targets for tumor therapy." (PMID 36185280, 2022). "PARP1 and PARP2 inhibitors have been developed for breast and ovarian tumors manifesting double-stranded DNA-repair defects, whereas tankyrase 1 and 2 (TNKS1 and TNKS2, also known as PARP5a and PARP5b, respectively) inhibitors have been developed for tumors with elevated β-catenin activity." (PMID 25286857, 2014).
anemia (1 paper, 2022). A reduction in the number of red blood cells, the amount of hemoglobin, and/or the volume of packed red blood cells. "When investigated, single CpG sites of both Fanconi anemia complementation group C (FANCC) and tankyrase 2 (TNKS2) showed differences in methylation patterns in the PD and control groups." (PMID 35053088, 2022).
cardiac hypertrophy (1 paper, 2022). "Specifically, both TNKS1 and TNKS2 were elevated in the infarct and border area in rat hearts undergoing cardiac remodeling and scar formation, whereas TNKS1 was continually increased in the infarct area in rats developing cardiac hypertrophy." (PMID 36077457, 2022).
cerebrovascular disorder (1 paper, 2017). A disorder resulting from inadequate blood flow in the vessels that supply the brain. "Finally, tankyrase-2 is found at rank 4 (4PNL_5, Tanimoto coefficient 0.3214, Z-score 2.96) and is associated to cardiovascular diseases and cerebrovascular disorders." (PMID 28449705, 2017).
cystic fibrosis (1 paper, 2020). Autosomal recessive disorder caused by pathogenic variants in the CFTR gene (cystic fibrosis transmembrane conductance regulator), which encodes a chloride and bicarbonate channel expressed in epithelial cells, and follow the diagnosis criteria. "TNKS2 (cg11963436) and LOC723972 (cg21581312) were reported to be among the 50 DM CpG sites associated with lung function in cystic fibrosis patients." (PMID 32605309, 2020).
glioma (1 paper, 2022). A benign or malignant brain and spinal cord tumor that arises from glial cells (astrocytes, oligodendrocytes, ependymal cells). "Of the eight investigated genes involved in telomere maintenance and telomerase regulation, three (PINX1, TNKS, and TNKS2) were found to be downregulated in all glioma cell lines when compared to individual controls." (PMID 36142793, 2022). "Expression of TNKS and TNKS2 was decreased in glioma cells compared to non-malignant cells and normal brain tissue." (PMID 36142793, 2022).
Hypertension (1 paper, 2022). The presence of chronic increased pressure in the systemic arterial system. "Notably, genome-wide association studies indicate that TNKS and TNKS2 (encoding TNKS1 and TNKS2) are associated with MI, ischemic stroke, and hypertension in humans, suggesting a crucial role for TNKSs in the pathogenesis of cardiovascular disease (CVD)." (PMID 36077457, 2022).
influenza (1 paper, 2025). An acute viral infection of the respiratory tract, occurring in isolated cases, in epidemics, or in pandemics; it is caused by serologically different strains of viruses (influenzaviruses) designated A, B, and C, has a 3-day incubation period, and usually lasts for 3 to 10 days. "They further demonstrated TNKS2 was targeted by a cellular microRNA (miR-206) that displays an anti-influenza function by inhibiting TNKS2." (PMID 40332127, 2025).
ischemic stroke (1 paper, 2022). A stroke disorder caused by obstruction of blood flow to the brain, due to thrombotic (local blood clot formation) or embolic (due to a blood clot or other material traveling from another site) event. "The association of TNKS and TNKS2 with CVD and ischemic stroke risk has also been identified by a whole genome survey of Caucasian women." (PMID 36077457, 2022).
liver cancer (1 paper, 2021). An epithelial or non-epithelial malignant neoplasm that arises from the liver. "High levels of TNKS1 and/or TNKS2 expression have been found in colon, lung, brain, breast, ovarian, and liver cancers." (PMID 34639169, 2021). "High levels of TNKS1 and/or TNKS2 expression have been observed mainly in colon, lung, brain, breast, ovarian, and liver cancers." (PMID 34639169, 2021).
lung adenocarcinoma (1 paper, 2013). A carcinoma that arises from the lung and is characterized by the presence of malignant glandular epithelial cells. "In the three evaluable human lung adenocarcinoma and normal lung pairs TNKS1 and TNKS2 levels were either moderately elevated or unchanged." (PMID 23621985, 2013). "The qPCR analysis of WIF1 and TNKS expression in three cases of human lung adenocarcinoma revealed the expected repression of WIF1 and moderate overexpression of TNKS2 (as compared to adjacent normal lung tissues) in all examined cases, as well as for TNKS1 in 1 of 3 cases." (PMID 23621985, 2013).
pituitary adenoma (1 paper, 2024). "Associations with pituitary adenoma recurrence: the TNKS2 rs10509637 AA genotype was associated with 4.2-fold increased odds of PA recurrence." (PMID 38339395, 2024). "TERF1 rs1545827, TNKS2 rs10509637 and rs10509639, TERF2 rs251796, ZNF676 rs412658, and CTC1 rs3027234 genes’ single nucleotide polymorphisms were analyzed to evaluate the associations with pituitary adenoma relapse." (PMID 38339395, 2024).
small cell lung carcinoma (1 paper, 2021). Small cell lung cancer (SCLC) is a highly aggressive malignant neoplasm, accounting for 10-15% of lung cancer cases, characterized byrapid growth, and early metastasis. "TNKS2 (DM: 18.4%, non-DM: 1.5%; p = 0.0004) also showed a high frequency of mutations in the diabetic group, and it is known to be associated with the incidence of small cell lung cancer." (PMID 35003350, 2021).
tuberculosis (1 paper, 2025). A chronic, recurrent infection caused by the bacterium Mycobacterium tuberculosis. "For example, circRNA-0045474 triggers macrophage autophagy in tuberculosis via the miR-582-5p/TNKS2 axis and circ-TRAPPC6B inhibits the growth of Mtb in macrophages and induces autophagy by targeting miR-874-3p." (PMID 39996735, 2025).
viral infections (1 paper, 2025). "In conclusion, TNKS1 and TNKS2 regulate influenza virus infection via type I interferon response.IMPORTANCEPoly (ADP-ribose) polymerases (PARPs) play a crucial role in DNA repair, cellular stress responses, epigenetics, gene transcription, and viral infections." (PMID 41036852, 2025).
ZIKV infection (1 paper, 2022). "miR-206, for instance, elicits its anti-influenza A virus activity by targeting tankyrase 2 to restrict viral replication, and miR-142-5p, whose accumulation is significantly inhibited by ZIKV, acts as an antiviral factor during ZIKV infection." (PMID 36389816, 2022).
cancer (13 papers, 2009 to 2025). A tumor composed of atypical neoplastic, often pleomorphic cells that invade other tissues. "The ZINC06804365 has been tested and reported as a potential inhibit for many signaling pathways such as Wnt-3a and also as having inhibitory activity against the Tankyrase-2 enzyme which reportedly has anti-cancer activities." (PMID 36551744, 2022). "Tankyrases (TNKS, TNKS2) are proteins involved in telomere length maintenance, which, together with regulation of the Wnt/β-catenin pathway, is important for cancer cell renewal and survival." (PMID 36142793, 2022). "Through interfering with telomerase activity, TNKS2 can induce the senescence process of cancer cells." (PMID 33849554, 2021). "The poly(ADP-ribose) polymerase (PARP) Tankyrase (TNKS and TNKS2) is paramount to Wnt-β-catenin signaling and a promising therapeutic target in Wnt-dependent cancers." (PMID 27494558, 2016). "In recent years, TNKS2 has emerged as potentially useful chemical probe for several cancers." (PMID 33849554, 2021). "Pharmacological inhibition of these enzymes may achieve desirable anti-tumor effects via AXIN stabilization with subsequent effective attenuation of downstream β-catenin signaling, and offer a new approach for the treatment of multiple cancers that over express TNKS1 or TNKS2." (PMID 26246473, 2015). "Tankyrase 1 (TNKS1) and tankyrase 2 (TNKS2) are two homologous proteins that are gaining increasing importance due to their implication in multiple pathways and diseases such as cancer." (PMID 33910596, 2021). "TNKS-2 and its close homolog TNKS-1 are positive regulators of telomere elongation, which is important for the perpetual growth of cancer cells." (PMID 19270793, 2009).
tumor (13 papers, 2013 to 2024). "The expression of IL‐18 and E‐cadherin was associated with tumor differentiation (P < 0.05), whereas the expression of β‐catenin, N‐cadherin, and TNKS2 was associated with tumor de‐differentiation (P < 0.05)." (PMID 30524946, 2018). "The expression of IL‐18 and E‐cadherin was associated with tumor differentiation, whereas the expression of β‐catenin, N‐cadherin, and TNKS2 was associated with tumor de‐differentiation." (PMID 30524946, 2018). "Elevated expression of IL‐18 (P < 0.01) and E‐cadherin (P = 0.034) was associated with tumor differentiation, whereas expression of TNKS2 (P < 0.01), β‐catenin (P = 0.012), and N‐cadherin (P < 0.01) was associated with tumor de‐differentiation." (PMID 30524946, 2018). "Tankyrase 2 (TNKS2) can be associated with longer telomeres in tumor cells when its expression is upregulated, suggesting that TNKS2 may promote tumor development and function as an oncogene." (PMID 38339395, 2024). "Further investigation systematically revealed that ICA induces cell-cycle arrest and apoptosis in SKOV-3 cells by blocking TNKS2/Wnt/β-catenin signaling via the tumor-suppressor miR-1-3p with transcriptome analysis." (PMID 36185280, 2022). "The2X-121, a small molecular targeting the PARP, as well as the tankyrases (TNKS1 and TNKS2), showed anti-tumor activity in patients with various types of solid tumor and are generally well tolerated in Phase 1 trial (NCT01618136)." (PMID 36185280, 2022). "Small-molecule tankyrase 1 and tankyrase 2 (TNKS1/2) inhibitors are effective antitumor agents in selected tumor cell lines and mouse models." (PMID 34337362, 2021). "The mRNA expression levels of both TNKS1 and TNKS2 were significantly elevated (P < 0.05) in HCC tumors compared to their matched non-tumor tissues." (PMID 26246473, 2015). "In this study, we confirmed the predominant over-expression of TNKS1 mRNA and protein levels in human HCC tumors compared to adjacent non-tumor liver tissues, whereas TNKS2 is elevated only at mRNA level." (PMID 26246473, 2015). "TNKS1 and/or TNKS2 levels were elevated in the majority of the paired tumor and normal murine transgenic cyclin E samples." (PMID 23621985, 2013). "As expected from the in vitro results, shRNA-mediated knockdown of TNKS1 and TNKS2 led to a significant decrease in syngeneic tumor formation after 8 weeks." (PMID 23621985, 2013). "In addition, tankyrase 2 (TNKS2), which belongs to the human telomere-associated poly (ADP-ribose) polymerase (PARP) family, was claimed to increase telomere length, thus enhancing tumor progression." (PMID 30833362, 2019). "In particular, compared to the vector control, CRL1623‐IL‐18‐injected tumor xenografts expressed high levels of IL‐18 (P < 0.01), β‐catenin (P = 0.028), TNKS2 (P = 0.045), and N‐cadherin (P = 0.068), but lower levels of E‐cadherin (P = 0.045), and thus the E/N ratio was changed." (PMID 30524946, 2018). "inhibition of tumor growth by induction of the tumor cell apoptosis pathway through glycogen synthase kinase 3β 9, 11 and promotion tumor cell EMT by activation of TNKS2 via the Wnt/β‐catenin signal pathway in vitro, and could therefore play a role in tumor metastasis." (PMID 30524946, 2018). "JW55 inhibiting PARP domain of tankyrase 1 and tankyrase 2, as well as JW67 and JW74 which suppress tumor growth in Apc mutant mice, have been introduced as drug candidates too." (PMID 33224221, 2020). "To determine the clinical significance of TNKS1 or TNKS2 in HCC, we first measured their mRNA expression levels in biopsies obtained from 29 HCC patients, in comparison to matched adjacent non-tumor tissues." (PMID 26246473, 2015). "We further detected TNKS1 and TNKS2 using Western blot in 20 pairs of HCC and matched non-tumor liver extracts, and observed elevated TNKS1 expression in 16 of 20 HCC patients (80%)." (PMID 26246473, 2015).
tumor (continued). "We report that expression of tankyrase 2 (TNKS2), β‐catenin, and N‐cadherin was higher in tumor cells than in normal mucosae, whereas the expression of IL‐18 and E‐cadherin was higher in normal than in tumor tissues." (PMID 30524946, 2018). "Knockdown of TNKS1 and TNKS2 in HCC cell lines by RNA interference resulted in inhibition of cell proliferation and reduction in nuclear β-catenin protein levels, validating the anti-tumor potential of inhibiting these enzymes in the WNT/β-catenin pathway." (PMID 26246473, 2015).
TNKS2 also shares sentences with these, for which no sentence is quoted: cardiovascular disease (2 papers); depression (2); acute myeloid leukemia (1); age-related macular degeneration (1); astrocytoma (1); bladder cancer (1); colon cancer (1); gastric cancer (1); gastric MALT lymphoma (1); HCMV infection (1); hepatic carcinoma (1); immune deficiency (1); infection (1); laryngeal carcinoma (1); lymphoma (1); melanoma (1); Nephropathy (1); non-small cell lung carcinoma (1); oral cancer (1); pancreatic cancer (1); peripheral T-cell lymphomas (1); triple-negative breast carcinoma (1).